RPL30 (ribosomal protein L30)
Description:
Component of the large ribosomal subunit. The ribosome is a large ribonucleoprotein complex responsible for the synthesis of proteins in the cell.
Synonyms: L30; eL30
Tractability: Small molecule: an approved drug acts on it; a structure with a bound ligand is known; a high-quality ligand is known. PROTAC: UniProt records ubiquitination sites on it; ubiquitination databases record sites on it; its protein half-life has been measured; a small molecule that binds it is known. Other modalities: a drug acting on it is in phase 2 or 3 trials.
Target class: Other cytosolic protein
Gene: Protein-coding gene on chromosome 8 (98,024,851 to 98,046,469, reverse strand). Ensembl gene ENSG00000156482.
Subcellular location: Cytoplasm
Subcellular location (Human Protein Atlas): Cytosol; Endoplasmic reticulum
Pathways (Reactome):
Metabolism of proteins: Eukaryotic Translation Termination; Formation of a pool of free 40S subunits; GTP hydrolysis and joining of the 60S ribosomal subunit; L13a-mediated translational silencing of Ceruloplasmin expression; PELO:HBS1L and ABCE1 dissociate a ribosome on a non-stop mRNA; Peptide chain elongation; Ribosome Quality Control (RQC) complex extracts and degrades nascent peptide; SRP-dependent cotranslational protein targeting to membrane; ZNF598 and the Ribosome-associated Quality Trigger (RQT) complex dissociate a ribosome stalled on a no-go mRNA
Metabolism of RNA: Major pathway of rRNA processing in the nucleolus and cytosol; Nonsense Mediated Decay (NMD) enhanced by the Exon Junction Complex (EJC); Nonsense Mediated Decay (NMD) independent of the Exon Junction Complex (EJC)
Cellular responses to stimuli: Response of EIF2AK4 (GCN2) to amino acid deficiency
Developmental Biology: Regulation of expression of SLITs and ROBOs
Disease: Viral mRNA Translation
Metabolism: Selenocysteine synthesis
Gene Ontology:
Molecular function: protein binding; RNA binding; structural constituent of ribosome
Biological process: antimicrobial humoral immune response mediated by antimicrobial peptide; cytoplasmic translation; defense response to Gram-negative bacterium; killing of cells of another organism; negative regulation of myoblast fusion; spermatogenesis; striated muscle contraction; translation
Cellular component: cytoplasm; cytosolic large ribosomal subunit; cytosolic ribosome; extracellular exosome; focal adhesion; membrane; nucleus; postsynaptic density; cytosol; synapse
Genetic constraint (gnomAD): Loss-of-function variants: 0 observed, 13.46 expected, observed/expected ratio (o/e) 0, 90% interval 0 to 0.22. The upper end of that interval is the gene's LOEUF score, 0.22, which puts it in group 1 of 6, group 1 being the genes least tolerant of losing a copy. Missense variants: 49 observed, 125.03 expected, observed/expected ratio (o/e) 0.39, 90% interval 0.31 to 0.5. Synonymous variants: 33 observed, 46.39 expected, observed/expected ratio (o/e) 0.71, 90% interval 0.54 to 0.95.
Homologues: Orthologues: tropical clawed frog rpl30 (97% identical), zebrafish rpl30 (97% identical), Drosophila melanogaster RpL30 (77% identical), Caenorhabditis elegans rpl-30 (72% identical), pig RPL30 (66% identical).
Diseases named in the same sentence as RPL30 in open-access papers:
RPL30 is named in the same sentence as 29 diseases in open-access papers, as found by Europe PMC text mining. Sharing a sentence is not in itself a finding about the gene and the disease. The quoted sentences say what the papers report.
hepatocellular carcinoma (4 papers, 2008 to 2024). A malignant tumor that arises from hepatocytes. "The mRNA level of RPS8, RPL12, RPL23A, RPL27, and RPL30 was detected as upregulated in hepatocellular carcinoma tissues and cell lines." (PMID 33584809, 2020). "Disease specific humoral immune responses against TBP-1, p27(BBP), and RPL30 have been induced in patients with hepatocellular carcinoma (HCC), and the antibodies against these antigens may be also used as tumour markers." (PMID 18691435, 2008). "The increased number of ribosomal protein L30 (RPL30) may play a central role in the CRC process and in induced hepatocellular carcinoma." (PMID 34208938, 2021).
medulloblastoma (4 papers, 2006 to 2024). A malignant, invasive embryonal neoplasm arising from the cerebellum. "The 8q-mapped RPL30 gene was associated with adverse outcomes in Medulloblastoma patients." (PMID 34760386, 2021). "We demonstrate that gain of 8q and expression levels of three 8q-mapped candidate genes (EEF1D, RPL30, RPS20) are associated with adverse outcome in medulloblastoma." (PMID 16968546, 2006). "Nonetheless, our results suggest that better appreciation of the relative contributions of EEF1D, RPL30, RPS20, and their associated regulatory mechanisms will impact our understanding of medulloblastoma biology." (PMID 16968546, 2006). "For example, the expression of RPL30 is negatively correlated with carcinogenesis process in medulloblastoma that is usually accompanied by desmoplasia and could thus serve as a prognosis biomarker." (PMID 32572450, 2021). "Likewise, the RPL30 gene has been suggested as one out of eight major genes that predict poor clinical outcomes in mucinous colorectal adenocarcinoma and is also informative for lethality in medulloblastoma." (PMID 38397997, 2024). "Alternatively, we assayed the expression of EEF1D, RPL30, and RPS20 with qRT-RTPCR in twelve available medulloblastoma specimens, including those analyzed by Affymetrix U133 Plus 2.0 microarrays." (PMID 16968546, 2006).
breast carcinoma (3 papers, 2016 to 2025). "For the TNBC group, RPL30 was placed first by all programs, apart from GeNorm which recommended RPL27 and RPLP1, the same as for all four breast cancer cell lines." (PMID 39838295, 2025).
prostate carcinoma (3 papers, 2018 to 2024). A carcinoma that arises from epithelial cells of the prostate gland. "In addition, RPL30 is one of seven genes whose expression levels have been proposed for diagnosing prostate cancer." (PMID 38397997, 2024).
colorectal cancer (2 papers, 2023 to 2025). A primary or metastatic malignant neoplasm that affects the colon or rectum. "Because FIRΔexon2 is detected in colorectal cancer tissues, the expressions of RPL30, RPL37A, RPL38, RPS14, and RPS29 mRNAs by the effect of FIRΔexon2 were examined in HCT116 cells." (PMID 38139171, 2023). "Not only in colorectal cancer (COAD), but RPS7, RPL8 and RPL30 also have higher expression in tumour tissues in various tumours, such as Thymoma (THYM) and large B‐cell Lymphoma (DLBC)." (PMID 40770837, 2025).
COVID-19 (2 papers, 2022 to 2024). A disease caused by infection with severe acute respiratory syndrome coronavirus 2. "Except for RPL30, upregulation of these genes consistently increased the HR of COVID-19 mortality (P range = 0.001 to 0.009, PCC range = 0.71 to 0.78)." (PMID 35547187, 2022). "Except RPL30, upregulation of all these genes correlated with increased HRs of COVID-19 mortality." (PMID 35547187, 2022).
melanoma (2 papers, 2016 to 2018). A malignant, usually aggressive tumor composed of atypical, neoplastic melanocytes. "Our results indicate that this amplification and the ensuing overexpression of RPL8 and RPL30 also occurs in subsets of melanoma, liver, prostate, lung, and head and neck cancers." (PMID 29530001, 2018). "Additionally, six cancer cohorts – prostate, breast, liver, lung, melanoma, and head and neck – contained tumor clusters distinguished by overexpression of RPL8, RPL30 and RPS20, with shared expression patterns of 19 other RPTs." (PMID 29530001, 2018).
cardiac ischemia (1 paper, 2025). "Unfortunately, the information on extra ribosomal functions of RPL30 in cardiac ischemia is currently available." (PMID 39641799, 2025).
colon cancer (1 paper, 2008). "Further analysis of the topological architectures of the network identified three known hub cancer genes (IL8; DES and ENO1), while two novel hub genes (RBM9 and RPL30) may define new central elements in the gene network specific to colon cancer." (PMID 18691435, 2008).
deafness (1 paper, 2014). An inherited or acquired condition characterized by the complete loss of the ability to hear from one or both ears. "Of them, 9 deafness genes expressed more in the apical turn (Pou4f3, Slc17a8, Tmc1, Crym, Otof, Ush1c, Pcdh15, Slc26a5, and Lhfpl5) and six were internal controls (Gapdh, Actb, Rps17, Rpl30, Atp6, and Ipo8)." (PMID 24676347, 2014).
glioma (1 paper, 2022). A benign or malignant brain and spinal cord tumor that arises from glial cells (astrocytes, oligodendrocytes, ependymal cells). "Pre-treatment with C646 significantly reduced the enrichment of genomic sites in CDH5 and ANGPT1, but not the housekeeping gene RPL30 in radiated cells, thus confirming that P300 HAT activity is essential for radiation stress-induced epigenetic rewiring in glioma cells." (PMID 36261421, 2022).
heart failure (1 paper, 2025). Inability of the heart to pump blood at an adequate rate to meet tissue metabolic requirements.
ischemia (1 paper, 2025). A hypoperfusion of the BLOOD through an organ or tissue caused by a PATHOLOGIC CONSTRICTION or obstruction of its BLOOD VESSELS, or an absence of BLOOD CIRCULATION. "The expression of RPL10A, RPL14, RPL30, RPS18, FAU-40 (RPS30), and RPSA (Laminin Receptor, LR) was assessed in the myocardial and EAT tissues of MI, CABG and HL swine models and in LVSCs and EATDS challenged with ischemia." (PMID 39641799, 2025). "Importantly, the EATDS-derived exosomes have been unveiled for their potential cardiac responses and our previous findings identified major ribosomal proteins including RPL10A, RPL14, RPL30, RPS18, FAU-40 (RPS30), and RPSA (Laminin Receptor, LR) in the vesicles of ischemia-challenged EATDS." (PMID 39641799, 2025).
malignant lymphoma (1 paper, 2021). "RPS21, MRPS28, RPL31, and RPL30 showed relatively higher protein expressions in some DLBCL and other malignant lymphoma tissues than the averaged expressions in normal tissues, though not significant." (PMID 34760386, 2021).
Obesity (1 paper, 2026). Accumulation of substantial excess body fat. "Key proteins like RPL30 were consistently regulated, indicating that EC might activate translational remodeling to adapt to metabolic stress in obesity." (PMID 41104591, 2026). "The consistent regulation of key proteins such as RPL30—a central component of the ribosome involved in protein synthesis—suggests that EC may activate fundamental mechanisms of translational remodeling, potentially serving as an adaptive response to metabolic stress in obesity." (PMID 41104591, 2026). "The differential expression of ribosomal proteins RPL30 and RAB11A following epicatechin supplementation holds significant physiological implications, particularly in obesity and metabolic regulation." (PMID 41104591, 2026).
osteosarcoma (1 paper, 2023). A usually aggressive malignant bone-forming mesenchymal neoplasm, predominantly affecting adolescents and young adults. "In response to stress, uS3/RPS3, uS4/RPS9, uS17/RPS11, eS24/RPS24, eL6/RPL6, uL13/RPL13A, eL14/RPL14, eL30/RPL30, eL42L/RPL36AL, and RACK1 in U2OS (human osteosarcoma) cells have O-linked β-N-acetylglucosamine (O-GlcNAc) modifications." (PMID 37047306, 2023).
renal carcinoma (1 paper, 2021). A carcinoma arising from the epithelium of the renal parenchyma or the renal pelvis. "Most of the genes have usually been investigated as prognostic biomarkers in renal cancer, and RPS18, RPL30, NME2, and RPS25 usually have been investigated as unfavorable predictors, while GAB2 has been reported as favorable predictor in renal cancer." (PMID 34208938, 2021).
tumor (16 papers, 2008 to 2026). "Increased expression of various ribosomal proteins (rpS8, rpL12, rpL23a, rpL27, and rpL30) have been associated with tumor growth." (PMID 32973493, 2020). "RPL30 reacts with the sera of HCC patients, and antibodies against RPL30 can be used as tumor markers." (PMID 40521004, 2025). "Tumour cells with upregulated stemness‐related ribosomal proteins (RPS7/RPL30/RPL8) evade TNF‐mediated clearance." (PMID 40770837, 2025). "In the TNF signalling communication network, we observed that high‐stemness tumour cells were less regulated by immune cells, suggesting a potential association between tumour cell stemness and immune evasion, consistent with poor RFS of RPS7, RPL8 and RPL30." (PMID 40770837, 2025). "Concurrently, tumour cells elevate stemness‐associated ribosomal proteins (RPS7, RPL8, RPL30), enabling evasion of TNF signalling‐mediated surveillance." (PMID 40770837, 2025). "Tumour cells showed elevated stemness‐associated ribosomal genes (RPS7, RPL8, RPL30), which serve as diagnostic/prognostic biomarkers and therapeutic targets." (PMID 40770837, 2025). "Meanwhile, TNFRSF18− T cells have exhibited stronger immunoregulatory activity through the TNF pathway, while tumour cells with high stemness characteristics (high expression of RPS7/RPL30/RPL8) were more resistant to TNF‐mediated immunoregulation." (PMID 40770837, 2025). "We further examined the expression of RPS7, RPL8 and RPL30 in other tumours using the GEPIA database." (PMID 40770837, 2025). "For instance, SNORA71E/SNHG11 is in the top 10 of over-expressed targets in all tumor types, SNORA72/RPL30 is in the top 10 for all tumor types but KIRCs and OVs, and SNORA5C/TBRG4 is only missing in UCECs, OVs, and GBMs shortlists." (PMID 32046192, 2020). "Also, the public scRNA‐seq data showed that RPS7, RPL8 and RPL30 in tumour cells were highly expressed relative to epithelial cells (Log2FC > 1)." (PMID 40770837, 2025). "Moreover, we show that tumour cells displayed elevated expression of stemness‐associated ribosomal genes (RPS7, RPL8, RPL30), peaking at stage T4, which correlated with poor prognosis and immune escape." (PMID 40770837, 2025). "In addition, it has been proposed that the dysregulations of HSPB1, ALDOB, and RPL30 are sufficient to trigger tumor progression." (PMID 30344796, 2018). "Finally, we validated their expression using qPCR in an additional set of tumor:matched normal samples that resulted in five genes (RPL30, RPL27, PSMC5, MTCH1, and OAZ1), out of which RPL30 and RPL27 were most stable and were abundantly expressed across the tissues." (PMID 30128175, 2018). "RPL30, RPL31, RPS25, and FAU positively correlated with tumor-infiltrating lymphocytes (TIL) and macrophages." (PMID 34760386, 2021). "In the top 10 altered couples for these tumor types, 9 are identical: SNORA13/EBP41L4A-AS1, SNORA27/RPL21, SNORA31/TPT1, SNORA71E/SNHG11, SNORA72/RPL30, SNORD102/RPL21, SNORD12/ZFAS1, SNORD12B/ZFAS1, and SNORD12C/ZFAS1." (PMID 32046192, 2020). "In addition, it has been proposed that the dysregulation of DNA methylation of RPL30, ALDOB, IGF2, and TIMP1 is sufficient to trigger tumor progression." (PMID 30344796, 2018).
cancer (11 papers, 2008 to 2025). A tumor composed of atypical neoplastic, often pleomorphic cells that invade other tissues. "In spite of some authors considering RPL30 as a classical reference gene for cancer research due to its stable expression, our results showed that the overexpression of RPL30 is a hallmark of the dead group in PaCa, being the highest overexpressed gene in this GDC cohort (26.06-fold on average)." (PMID 38397997, 2024). "Other recurrent RPT expression patterns across cancer cohorts involved RPS4X, RPL13, RPL8 and RPL30." (PMID 29530001, 2018). "Notably, RPL30 and FAU genes were consistently upregulated in all six different cancer types identified." (PMID 34760386, 2021).
infection (4 papers, 2013 to 2021). The state of being infected such as from the introduction of a foreign agent such as serum, vaccine, antigenic substance or organism. "Both GAPDH and RPL30 possess a pattern of histone modifications typical of permissive chromatin, similar to those associated with most CMV viral loci during late times of infection." (PMID 25166009, 2014). "In conclusion, RPL30 and SDHA could be used as reference genes for the standardization of in CEF gene response to the infection with ALV-J, whereas commonly used ACTB and GAPDH are unsuitable to be reference genes in ALV-J/CEF settings." (PMID 24099561, 2013).
head and neck tumor (1 paper, 2018). "Our data suggest that RPL30 or RPL27 in combination with either PSMC5 or MTCH1 or OAZ1 can be used as a minimal set of control genes in head and neck tumor gene expression studies." (PMID 30128175, 2018).
RPL30 also shares sentences with these, for which no sentence is quoted: diabetic retinopathy (2 papers); proliferative diabetic retinopathy (2); colitis (1); head and neck cancer (1); mucinous colorectal adenocarcinoma (1); oral squamous cell carcinoma (1); ovarian tumours (1); prion disease (1).